ABCB4 (ATP binding cassette subfamily B member 4)
Description:
[Isoform 1]: Energy-dependent phospholipid efflux translocator that acts as a positive regulator of biliary lipid secretion. Functions as a floppase that translocates specifically phosphatidylcholine (PC) from the inner to the outer leaflet of the canalicular membrane bilayer into the canaliculi of hepatocytes. Translocation of PC makes the biliary phospholipids available for extraction into the canaliculi lumen by bile salt mixed micelles and therefore protects the biliary tree from the detergent activity of bile salts. Plays a role in the recruitment of phosphatidylcholine (PC), phosphatidylethanolamine (PE) and sphingomyelin (SM) molecules to nonraft membranes and to further enrichment of SM and cholesterol in raft membranes in hepatocytes. Required for proper phospholipid bile formation (By similarity). Indirectly involved in cholesterol efflux activity from hepatocytes into the canalicular lumen in the presence of bile salts in an ATP-dependent manner. Promotes biliary phospholipid secretion as canaliculi-containing vesicles from the canalicular plasma membrane. In cooperation with ATP8B1, functions to protect hepatocytes from the deleterious detergent activity of bile salts. Does not confer multidrug resistance (By similarity).
Synonyms: MDR3; PGY3; MDR2; PFIC-3; GBD1; ABC21; ICP3; MDR2/3
Tractability: Small molecule: a structure with a bound ligand is known. Antibody: UniProt places it where antibodies can reach, with high confidence; its Gene Ontology location is reachable by antibodies, with high confidence; UniProt predicts a signal peptide or a membrane-spanning region. PROTAC: ubiquitination databases record sites on it; its protein half-life has been measured; a small molecule that binds it is known.
Target class: ATP-binding cassette; ABCB subfamily; Transporter; Primary active transporter
Safety:
Unwanted effects reported when the protein is acted on. In parentheses: how it was acted on, where the effect was seen, and who reports it.
cardiotoxicity (source: ClinPGx)
Gene: Protein-coding gene on chromosome 7 (87,401,696 to 87,480,435, reverse strand). Ensembl gene ENSG00000005471.
Subcellular location: Cell membrane; Apical cell membrane; Membrane raft; Cytoplasm; Cytoplasmic vesicle, clathrin-coated vesicle
Subcellular location (Human Protein Atlas): Nucleoplasm; Plasma membrane; Cytosol; Focal adhesion sites
Pathways (Reactome):
Disease: Defective ABCB4 causes PFIC3, ICP3 and GBD1
Metabolism: PPARA activates gene expression
Transport of small molecules: ABC-family protein mediated transport
Gene Ontology:
Molecular function: ATPase-coupled transmembrane transporter activity; ceramide floppase activity; phosphatidylcholine floppase activity; protein binding; ATPase-coupled intramembrane lipid transporter activity; phospholipid transfer activity; ABC-type transporter activity; ATP binding; ATP hydrolysis activity
Biological process: cellular response to bile acid; ceramide translocation; lipid homeostasis; phospholipid translocation; positive regulation of cholesterol transport; positive regulation of phospholipid translocation; positive regulation of phospholipid transport; bile acid secretion; lipid metabolic process; response to fenofibrate; transmembrane transport
Cellular component: apical plasma membrane; cytoplasm; cytosol; extracellular exosome; membrane raft; plasma membrane; membrane; clathrin-coated vesicle; intercellular canaliculus
Genetic constraint (gnomAD): Loss-of-function variants: 69 observed, 135.28 expected, observed/expected ratio (o/e) 0.51, 90% interval 0.42 to 0.62. The upper end of that interval is the gene's LOEUF score, 0.62, which puts it in group 2 of 6, group 1 being the genes least tolerant of losing a copy. Missense variants: 1,164 observed, 1,546.9 expected, observed/expected ratio (o/e) 0.75, 90% interval 0.72 to 0.79. Synonymous variants: 488 observed, 567.46 expected, observed/expected ratio (o/e) 0.86, 90% interval 0.8 to 0.93.
Gene-disease validity (ClinGen):
ClinGen rates the evidence that ABCB4 causes each of these diseases.
progressive familial intrahepatic cholestasis type 3 (autosomal recessive): Definitive. Progressive familial intrahepatic cholestasis type 3 (PFIC3), a type of progressive familial intrahepatic cholestasis (PFIC), is a late-onset hereditary disorder in bile formation that is hepatocellular in origin.
Homologues: Orthologues: chimpanzee ABCB4 (99% identical), macaque ABCB4 (98% identical), dog ABCB4 (91% identical), mouse Abcb4 (91% identical), rat Abcb1b (82% identical), tropical clawed frog abcb1 (68% identical), zebrafish abcb4 (63% identical), Caenorhabditis elegans pgp-9 (45% identical), Caenorhabditis elegans pgp-1 (43% identical), Caenorhabditis elegans pgp-12 (38% identical), Caenorhabditis elegans pgp-14 (37% identical), Caenorhabditis elegans pgp-6 (35% identical), and 4 more. Paralogues in human: ABCB1 (76% identical), ABCB5 (54% identical), ABCB11 (50% identical), ABCB9 (18% identical), ABCB10 (17% identical), ABCB8 (16% identical), TAP1 (16% identical), TAP2 (15% identical), ABCB6 (15% identical), ABCB7 (14% identical).
Diseases named in the same sentence as ABCB4 in open-access papers:
ABCB4 is named in the same sentence as 163 diseases in open-access papers, as found by Europe PMC text mining. Sharing a sentence is not in itself a finding about the gene and the disease. The quoted sentences say what the papers report.
cholestasis (106 papers, 2007 to 2026). Impairment of the bile flow caused by obstruction within the liver, or outside the liver in the bile duct system. "Mutations in ABCB4 (PFIC3/MDR3 deficiency) are associated with progressive cholestasis, moderate to severe pruritus, extrahepatic manifestation, and increased risk of hepatobiliary malignancies." (PMID 41601986, 2026). "Our observations align with recent research indicating that heterozygous ABCB4 variants are frequently seen in adults with cholestasis." (PMID 41436587, 2025). "In contrast, individuals carrying heterozygous ABCB4 pathogenic variants are prone to developing various conditions, including cholelithiasis, cholestasis induced by medications, pregnancy-related intrahepatic cholestasis, and cirrhosis." (PMID 40870862, 2025). "Specifically, ABCB4 variants have been shown to predispose to adult biliary cirrhosis, gallstone, gallbladder and bile duct carcinoma, drug induced cholestasis and low phospholipid associated cholelithiasis (LPAC) 10–14." (PMID 41436587, 2025). "Deficiency caused by mutations in ABCB4 can lead to bile duct damage caused by bile salts, resulting in cholestasis and liver fibrosis." (PMID 38610052, 2024). "Both Abcb4-deficient mice were found to have elevated total bile acid serum levels, indicating that Abcb4 deletion induced cholestasis within a short period in both CYPDKO and wild-type mice." (PMID 39111549, 2024). "PFIC3 is associated with biallelic mutations of ABCB4, clinically characterized by cholestasis with jaundice and pruritus." (PMID 38610052, 2024). "Abcb4 gene-deficient mice established as animal models of PFIC3 exhibit cholestasis-induced liver injury." (PMID 39111549, 2024). "Mutations in ABCB4 can also induce cholestasis since molecular studies from tissue culture suggest that xenobiotics can inhibit P-glycoproteins." (PMID 36982896, 2023). "Studies performed during these last years concerning the iDILI phenotype have shown that ABCB4 deficiency predisposes to DIC: xenobiotics that inhibit these P-glycoproteins can also induce cholestasis in predisposed patients with ABCB4 variants." (PMID 36982896, 2023). "It has been shown that cholestasis was associated with reduced messenger RNA (mRNA) expression of Srebp1 and diminished lipogenesis in Abcb4-/- mice." (PMID 34954190, 2022). "The aim of our study was to investigate the role of the cholestasis-associated variant ABCB4 c.711A > T (p.I237I, rs2109505) in patients with primary biliary cholangitis (PBC) and primary sclerosing cholangitis (PSC)." (PMID 36397154, 2022). "We believe that for an accurate diagnosis of PFIC3 and exclusion of other causes of cholestasis, immunohistochemistry staining of liver specimens for MDR3 and molecular genetic analysis of ABCB4 are essential." (PMID 36569137, 2022). "Cholestasis, particularly because of Abcb4-/-, leads to a loss of barrier function of bile ducts caused by changes in the tight junctions." (PMID 34954190, 2022). "Such oestroprogestative induced cholestasis has been reported in female patients carrying a monoallelic variant in ABCB4 and ABCB11." (PMID 35626323, 2022). "Transient neonatal cholestasis has been reported with heterozygous mutations in both ABCB4 and ABCB11 (Bile Salt Exporter Protein)." (PMID 37207060, 2021). "The risk of cholestasis in pregnancy has been associated with genetic variants in ABCB4, ABCB11, ATP8B1, ABCC2, and TJP2 genes." (PMID 34557220, 2021). "We report a 3-month-old male with cholelithiasis and transient neonatal cholestasis in the setting of combined pathogenic heterozygous mutations in the genes ABCB4 and ABCB11." (PMID 37207060, 2021). "We investigated the effects of Abcb4−/−-induced cholestasis in two distinct models, Abcb4-deficient mice (Abcb4−/−) and HBs overexpressing mice as well as chimera of both, knockout and transgene, on BALB/c genetic background (HBs, HBs/Abcb4−/−)." (PMID 32612285, 2020).
cholestasis (continued). "The diagnosis is suspected in cholecystectomies patients around 40 years old with associated cholestasis and is confirmed by ABCB4 genotyping." (PMID 32168787, 2020). "Loss of functional ABCB11 and ABCB4 proteins causes early-onset refractory cholestasis or cholangiopathy." (PMID 31886153, 2019). "Defects in genes coding for bile salt transporter proteins (BSEP/ABCB11, FIC1/ATP8B1 and MDR3/ABCB4) cause cholestasis leading to the release of inflammatory cytokines, chronic inflammation and subsequent cholangiocarcinogenesis." (PMID 30819129, 2019). "Mice lacking the ATP-binding cassette ABCB4 protein encoded by the Mdr2 gene (Mdr2-/-) provide a model for the study of cholestasis in the context of chronic inflammation as a result of increased BA accumulation." (PMID 30237481, 2018). "Mutations in ABCB4 cause cholestasis, which is characterised by the decreased biliary lecithin output, impaired formation of mixed micelles, and the production of more hydrophilic bile with potent detergent properties, resulting in membrane damage." (PMID 30148122, 2018). "Some genetic forms of cholestasis have been found to be associated with specific mutations in the ABCB4 (MDR3) and ABCB11 (BEP) genes." (PMID 29221149, 2017). "Notably, while comprehensive genetic screening excluded mutations in other cholestasis-associated genes (ABCB4, FXR, TJP2, MYO5B, and USP53), both cases carried the p.A1028A concurrently with p.V444A." (PMID 40776909, 2025). "Notably, a study in Switzerland found that ABCB4 variants were present in 50% of individuals assessed for unexplained biochemical cholestasis, ICP, or other cholestatic phenotypes." (PMID 41436587, 2025). "Genetic testing revealed a novel ABCB4 gene mutation linked to cholestasis." (PMID 40110281, 2025). "BSEP inhibition by drugs leads to reduced BAs’ secretion and their retention within hepatocytes, exiting in cholestasis, while mutations in the ABCB4 gene expose the biliary epithelium to the injurious detergent actions of BAs, thus increasing susceptibility to DIC." (PMID 36982896, 2023). "Furthermore, similar findings were observed in mouse models of cholestasis induced by BDL, 0.1%DDC feeding, or Abcb4 gene deficiency, confirming the observations in patients with cholestasis." (PMID 36690641, 2023). "In addition, the ABCB4 mutations were also associated with cholestasis in pregnancy, liver, gallbladder and bile duct cancer, cirrhosis and increased serum levels of liver-related biomarkers, including transaminases and GGT." (PMID 35884482, 2022). "As a result of ABCB4 variants or other mutations in cholestasis-related genes, these subjects often present serum liver enzyme abnormalities, particularly alanine aminotransferase, aspartate amino-transferase and GGT, in the absence of a clear aetiology of liver injury." (PMID 35884482, 2022). "Thereby, immunohistochemistry for ABCB11 and ABCB4 could be a useful diagnostic tool to determine the extent of cholestasis and disease progression in PSC." (PMID 31886153, 2019). "Moreover, heterozygous mutations in the ABCB4 gene have been described in patients with ICP as well as adults with unexplained anicteric cholestasis and pronounced liver fibrosis." (PMID 31886153, 2019). "In addition to familial intrahepatic cholestasis, partial defects in ATP8B1, ABCB11, and ABCB4 predispose patients to drug-induced cholestasis and intrahepatic cholestasis in pregnancy." (PMID 30148122, 2018). "Our results also agreed with clinical observations in patients exhibiting low phospholipid-associated cholestasis, gallbladder cholesterol cholelithiasis, cirrhosis and other diseases caused by loss of function mutations of MDR3, the human homolog of the AbcB4 mouse gene." (PMID 29125588, 2017).
cholestasis (continued). "Many reports demonstrate that in MDR2KO mice, the ablation of the AbcB4 gene, encoding the MDR2 protein, a hepatocyte membrane protein with function in phospholipid transport into the biliary ducts, results in hepatic cholestasis due to toxic bile accumulation." (PMID 29125588, 2017). "ABCB4 deficiency also causes cholestasis, and might be expected to cause cholangitis and predispose to liver cancer." (PMID 28220208, 2017). "Defect in ABCB4 function causes the production of bile with low phospholipid content, increased lithogenicity and high detergent properties leading to bile duct luminal membrane injuries and resulting in cholestasis with increased serum GGT activity." (PMID 17562004, 2007). "Therefore, ABCB4 deficiency results in cholangitis and cholestasis-induced liver injury." (PMID 39111549, 2024). "In Mdr2KO mice, the ablation of ABCB4 gene encoding for the multidrug resistance protein 2 (Mdr2), a membrane protein with flippase activity and a role in the hepato-canalicular transport of phospholipids, results in bile retention in the liver and cholestasis-induced hepatic fibrosis." (PMID 32994489, 2020). "In both of the patient case studies, relatives heterozygous for the same I490T and S978P variants presented with cholestatic diseases that are more commonly associated with ABCB4 dysfunction, suggesting that pre-existing cholestasis may also predispose to cancerogenesis in humans." (PMID 28220208, 2017). "Defect in ABCB4 function causes the production of bile with low phospholipid content, increased lithogenicity and high detergent properties leading to bile duct luminal membrane injuries and resulting in cholestasis with increased serum gamma-glutamyltransferase (GGT) activity." (PMID 17562004, 2007). "Primary biliary cholangitis often coexists with autoimmune thyroid disorders, such as Hashimoto’s thyroiditis, where hypothyroidism exacerbates cholestasis by disrupting ABCB4-mediated biliary phospholipid excretion." (PMID 41524244, 2026). "A review identified phenotypes of ABCB4 deficit in addition to PFIC3, DIC, and ICP: chronic cholangiopathy, adult biliary fibrosis/cirrhosis, some cases of transient neonatal cholestasis, and parenteral nutrition-associated liver disease." (PMID 39984942, 2025). "Homozygous variants of ABCB4 and ABCB11 genes, bile constituent transporters, can lead to severe cholestasis." (PMID 40022113, 2025). "BSEP and ABCB4 play crucial roles in facilitating the secretion of BAs into the bile canaliculi, thereby ameliorating cholestasis and reducing cytotoxicity." (PMID 40677400, 2025). "Among the 356 adult patients of a study on variants in cholestasis-related genes in adults, 101 were identified as carriers of variants of the genes ATP8B1, ABCB11, and ABCB4, often in heterozygosity." (PMID 39984942, 2025). "When transaminase abnormalities with elevated GGT levels, liver fibrosis, and cholestasis are identified clinically in a patient, ABCB4-related liver diseases should be considered." (PMID 38610052, 2024). "Homozygous variants or compound heterozygous variants in ABCB4 and ABCB11 can cause a spectrum of disease from moderate cholestasis to severe progressive familial intrahepatic cholestasis (PFIC), PFIC3 and PFIC2 respectively." (PMID 39262913, 2024). "Previous studies demonstrated that the genetic disruption of Mdr2 (Abcb4), a mouse ortholog of the human MDR3 (ABCB4) gene, caused a depletion of the phosphatidylcholine from bile, leading to liver cholestasis and injury." (PMID 38994954, 2024). "Dietary lecithin has been shown to reduce cholestasis symptoms in Abcb4−/− mice by decreasing serum levels of cholic acid and bilirubin, and reducing bile duct hyperplasia and activation of fibroblasts around the bile duct." (PMID 37324459, 2023).